FAR2P1 (fatty acyl-CoA reductase 2 pseudogene 1)
Synonyms: LOC440905
Gene: Transcribed unprocessed pseudogene on chromosome 2 (130,028,309 to 130,040,560, reverse strand). Ensembl gene ENSG00000180178.
Diseases named in the same sentence as FAR2P1 in open-access papers:
FAR2P1 is named in the same sentence as 4 diseases in open-access papers, as found by Europe PMC text mining. Sharing a sentence is not in itself a finding about the gene and the disease. The quoted sentences say what the papers report.
tumor (1 paper, 2022). "The fatty acid metabolic pathway requires the generation of fatty acyl coenzyme A. FAR2P1, as a reductase of fatty acyl coenzyme A, may be involved in tumor cell progression through fatty acid metabolism." (PMID 36514150, 2022).
FAR2P1 also shares sentences with these, for which no sentence is quoted: lung adenocarcinoma (1 paper); metastatic tumor (1); non-small cell lung carcinoma (1).